GINS2 (GINS complex subunit 2)
Diseases named in the same sentence as GINS2 in open-access papers (continued):
Sharing a sentence is not in itself a finding about the gene and the disease.
lung adenocarcinoma (4 papers, 2013 to 2021). A carcinoma that arises from the lung and is characterized by the presence of malignant glandular epithelial cells. "The expression status of GINS2 was determined in patients with lung adenocarcinoma and the PCT by immunohistochemistry." (PMID 33391406, 2021). "In the present study, GINS2 mRNA was observed to be significantly highly expressed in stage II lung adenocarcinoma for the first time." (PMID 24137407, 2013). "Compared with the stage I and IIIA samples, the stage II lung adenocarcinoma samples were marked by two differentially-expressed genes (GINS2 and LY6K)." (PMID 24137407, 2013). "The relative expression levels of Zimp7 mRNA in the lung adenocarcinoma patients of stages I, II and IIIA were 4.04±0.86, 1.35±0.32 and 1.67±0.40, respectively, and for the GINS2 mRNA, the levels were 2.15±0.95, 12.23±3.27 and 5.01±1.02, respectively." (PMID 24137407, 2013). "Interestingly, while many of the genes are highly connected, four of the HUB genes upregulated during lung adenocarcinoma (MCM10, MCM4, GINS2 and CD45) are predicted to interact nearly independently through direct binding mechanisms." (PMID 33604163, 2021). "Moreover, we compared GINS2 expression in lung squamous cell carcinoma (LSCC), large cell lung cancer (LCLC) and adenocarcinoma of the lung (ACL)." (PMID 33391406, 2021).
lung carcinoma (4 papers, 2020 to 2023). "After silencing GINS2 in A549 cells, we performed MTT assays, flow cytometry assays, colony formation assays, cell cycle analyses and RNA sequence analysis to elucidate the effect of GINS2 on lung cancer." (PMID 33391406, 2021). "In subsequent studies, we selected A549 cells to evaluate the effect of GINS2 and to determine its function in lung cancer." (PMID 33391406, 2021). "To reveal the mechanism of GINS2 in lung cancer, we collected A549 cells with GINS2 knockdown to examine the downstream gene expression changes." (PMID 33391406, 2021). "The TCGA database analysis demonstrated that GINS2 mRNA and protein was highly expressed in three kinds of lung cancer tissues." (PMID 33391406, 2021). "In the TCGA database analysis, a significant correlation between increased GINS2 expression and carcinogenesis of lung cancer was observed." (PMID 33391406, 2021). "In present study, we determined the clinical significance of GINS2 in lung cancer and inhibited the proliferation of lung cancer cells by inhibiting the signal transducer and activator of transcription (STAT) signaling pathway." (PMID 33391406, 2021). "In the present study, we further explored the role of GINS2 silencing in the apoptosis of lung cancer cells." (PMID 32181475, 2020). "GINS2 inhibits lung cancer progression by inhibiting the STAT signal pathway." (PMID 37600786, 2023). "We performed TCGA database analysis to confirm the clinical significance of GINS2 in lung cancer." (PMID 33391406, 2021). "We initially detected GINS2 mRNA expression in human lung cancer cell lines." (PMID 33391406, 2021). "However, the effect of GINS2 in lung cancer remains unclear." (PMID 33391406, 2021). "Furthermore, GINS2 inhibits the proliferation of NSCLC by inhibiting the STAT signaling pathway, which may be a potential biomarker for the diagnosis or prognosis of lung cancer." (PMID 33391406, 2021). "Our results suggest that GINS2 inhibits the proliferation of lung cancer cells by inhibiting the STAT signaling pathway, which may be a potential biomarker for the diagnosis or prognosis of lung cancer." (PMID 33391406, 2021). "However, the significance of GINS2 in lung cancer has not been investigated." (PMID 32181475, 2020).
melanoma (4 papers, 2017 to 2021). A malignant, usually aggressive tumor composed of atypical, neoplastic melanocytes. "The lncRNA X-inactive specific transcript (XIST) is overexpressed in melanoma and regulates the following miRNA-mRNA axes: miR-23a-3p/GINS complex subunit 2 (GINS2) and 139-5p/Rho associated coiled-coil containing protein kinase 1 (ROCK1)." (PMID 34638331, 2021).
non-small cell lung carcinoma (4 papers, 2020 to 2023). A group of at least three distinct histological types of lung cancer, including non-small cell squamous cell carcinoma, adenocarcinoma, and large cell carcinoma.
sarcoma (4 papers, 2022 to 2024). A usually aggressive malignant neoplasm of the soft tissue or bone. "Similarly, the increased GINS2 expression in sarcoma patients was associated with poor OS and DFS." (PMID 36092720, 2022). "In human sarcoma, our results revealed that the expression level of GINS2 in sarcoma tissues was higher than it in normal tissues." (PMID 35896011, 2022). "Consistent with the literature, our study found that GINS2 was upregulated in sarcomas and overexpressed in sarcoma cell lines." (PMID 36092720, 2022). "GINS1, GINS2 and GINS4 were positively correlated with the immune cell infiltration in sarcoma microenvironment." (PMID 35896011, 2022). "The GEPIA and Kaplan-Meier Plotter was used to make the investigation of the prognostic ability of GINS1, GINS2, GINS3 and GINS4 expression levels in sarcoma." (PMID 35896011, 2022). "Using the GEPIA dataset, we compared the expression of GINS mRNAs in sarcoma and normal tissues, it indicated that the expression levels of GINS1, GINS2 and GINS3 in sarcoma were statistically higher than in normal samples." (PMID 35896011, 2022). "In addition, the mRNA expression levels of the four GINS family members (GINS1, GINS2, GINS3, GINS4) were all higher in sarcoma tissue." (PMID 38473259, 2024). "The prognostic relevance tested was also obvious, increased expression of GINS1, GINS2, GINS3 and GINS4 may provide us new therapeutic targets for the treatment of sarcoma." (PMID 35896011, 2022). "By interrogating CCLE, we detected the transcription level of GINS members in many types of cancer cell lines, and got the conclusion that GINS1, GINS2 GINS3 and GINS4 were highly expressed in sarcoma cell lines including Ewing's sarcoma, osteosarcoma and chondrosarcoma." (PMID 35896011, 2022). "The high expression level of GINS1, GINS2 and GINS4 could reduce immune cell infiltration in the sarcoma microenvironment." (PMID 35896011, 2022). "GINS2 and GINS4 expression in sarcoma also affected the OS, although there was no statistical significance." (PMID 36092720, 2022).
liver cancer (3 papers, 2018 to 2022). An epithelial or non-epithelial malignant neoplasm that arises from the liver. "To gain new insights into the underlying roles of GINS2 in liver cancer and its underlying mechanism, we applied a bioinformatic analysis based on public database." (PMID 35069907, 2022). "Similarly, GINS2 mRNA expression showed 1.569-fold elevation from Roessler Liver dataset (P=5.47E-33) in liver cancer samples." (PMID 30413605, 2018).
ovarian carcinoma (3 papers, 2019 to 2022). A malignant neoplasm originating from the surface ovarian epithelium. "It was found that low mRNA expression of MCM3 (HR 0.75 [0.58–0.97], P = 0.027) was associated with worse overall survival for ovarian cancer patients, as well as GINS2 (HR 0.75 [0.58–0.97], P = 0.026)." (PMID 31703725, 2019). "In this study, GINS2 was found to be a potential target of miR-502-5p, and the upregulation of miR-502-5p inhibited the proliferation and migration of ovarian cancer cells through GINS2." (PMID 34288816, 2021).
prostate carcinoma (3 papers, 2018 to 2024). A carcinoma that arises from epithelial cells of the prostate gland. "The first three genes with the highest GINS2 gene change rate occurred in prostate cancer (5.47% in 494 cases), uterine sarcoma (5.26% in 57 points), and invasive breast carcinoma (2.58% in 1084 cases)." (PMID 36466552, 2022). "In prostate cancer, overexpression of Male Germ Cell-Associated Kinase (MAK), a male-specific kinase and co-activator of androgen receptor leads to increased expression level of GINS2 by mRNA profiling." (PMID 30413605, 2018).
cutaneous melanoma (2 papers, 2021 to 2022). A primary melanoma arising from atypical melanocytes in the skin. "Our results revealed several novel biomarkers and biological pathways that participate in the pathogenesis of cutaneous melanoma, and demonstrated the diagnostic and prognostic value of CDC45, CENPF, DTL, FANCI, GINS2, HJURP, TPX2 and TRIP13." (PMID 33531976, 2021).
glioblastoma (2 papers, 2017 to 2022). The most malignant astrocytic tumor (WHO grade IV). "In addition, the expression of GINS2 is associated with immune microenvironment and immune infiltration, especially in brain lower-grade glioma, lung squamous cell carcinoma, TGCT, breast invasive carcinoma, and glioblastoma multiforme." (PMID 36466552, 2022).
osteosarcoma (2 papers, 2022 to 2023). A usually aggressive malignant bone-forming mesenchymal neoplasm, predominantly affecting adolescents and young adults. "To systemically study the role of GINS2 in osteosarcoma (OS), we analyzed the protein levels of GINS2 in 59 OS tissues with 8 normal tissues by immunohistochemistry (IHC) and found that the protein levels of GINS2 are significantly elevated in OS tissues (P < 0.01)." (PMID 36873736, 2023). "GINS2 is overexpressed in several cancers, but little is known about its role in osteosarcoma (OS)." (PMID 36873736, 2023). "From a bioinformatics study, GINS2 may be an immunotherapy response prediction in osteosarcoma." (PMID 36873736, 2023).
primordial dwarfism (2 papers, 2022). "Through exome sequencing, a homozygous missense variant NM_016095.2:c.341G>T, p.(Arg114Leu), was identified in the GINS2 gene (MIM*610609) as the most likely candidate genetic cause of the observed primordial dwarfism and craniosynostosis phenotype." (PMID 34353863, 2022).
brain injury (1 paper, 2022). Acute and chronic (see also brain INJURIES, CHRONIC) injuries to the brain, including the cerebral hemispheres, CEREBELLUM, and brain STEM. "In experiments of mice, alcohol stimulated inflammatory cytokines and GINS2 knockdown further promoted them, while GINS2 knockdown promoted the alcohol-induced NF-κB activity of microglia, suggesting that GINS2 had a protective mechanism in alcohol-induced brain injury." (PMID 35896011, 2022).
breast tumors (1 paper, 2013). "A high level of GINS2 expression has been observed among metastasizing breast tumors." (PMID 24137407, 2013).
craniosynostosis (1 paper, 2022). Craniosynostosis is defined as the premature fusion of one or more cranial sutures leading to secondary distortion of skull shape resulting in skull deformities with a variable presentation. "We describe a patient with growth delay, craniofacial dysmorphisms and craniosynostosis, and in whom a homozygous missense variant in the GINS2 gene was identified." (PMID 34353863, 2022). "In summary, we report an individual with a homozygous likely disease-causing variant in GINS2 and with clinical features overlapping those of MGORS, including prenatal and postnatal growth delay, hypoplastic patellae and typical craniofacial dysmorphisms, such as microtia and craniosynostosis." (PMID 34353863, 2022).
dedifferentiated liposarcoma (1 paper, 2022). A high-grade subtype of liposarcoma (LS) that progresses from well-differentiated liposarcoma (WDLS), and most often occurs in the retroperitoneum. "Highly expressed GINS2 was also found in Pleomorphic Liposarcoma, Myxofibrosarcoma, Leiomyosarcoma, Dedifferentiated Liposarcoma, Myxoid/Round Cell Liposarcoma, with fold changes of 2.231, 2.729, 2.892, 2.046 and 2.351 respectively, compared with normal tissues through Barretina Sarcoma dataset." (PMID 35896011, 2022).
head and neck squamous cell carcinoma (1 paper, 2025). A squamous cell carcinoma that arises from any of the following anatomic sites: lip and oral cavity, nasal cavity, paranasal sinuses, pharynx, larynx, and salivary glands. "GINS2 is overexpressed in head-and-neck squamous cell carcinoma and promotes tumor progression by altering RRM2 expression, and systems analyses nominate GINS2 as an upstream modulator of metastatic programs in HNSCC." (PMID 41322418, 2025).
lentivirus infection (1 paper, 2023). Virus diseases caused by the Lentivirus genus. "STAT3 was overexpressed in the GINS2 knockdown cell lines by lentivirus infection." (PMID 36873736, 2023).
oral squamous cell carcinoma (1 paper, 2025). "The GINS complex subunit 2 (GINS2) is crucial for DNA replication, but its specific roles in oral squamous cell carcinoma (OSCC) pathogenesis and tumor microenvironment (TME) modulation are poorly defined." (PMID 41322418, 2025).
promyelocytic leukaemia (1 paper, 2020). "Meanwhile, knockdown of GINS2 obviously increases the number of cells in G2 phase, blocks DNA synthesis and decreases proliferation in the human promyelocytic leukaemia cell line HL60." (PMID 32181475, 2020).
steatosis (1 paper, 2021). Increased lipid within the cytoplasm of cells. "Eventually, we determined 10 hub genes (Down-regulated genes: MYC, TGFB3, ADAMTS1, THBS1, RASD1, PCDH20; Up-regulated genes: MAMDC4, CYP7A1, GINS2, and PDLIM3) related to NAS and steatosis." (PMID 34777484, 2021).
tumor (27 papers, 2013 to 2025). "GINS2 expression also correlated with neutrophil infiltration; GINS2 overexpression increased tumor-associated neutrophils (TANs) in vivo, and Ly6G neutrophil depletion attenuated GINS2-driven tumor enhancement." (PMID 41322418, 2025). "To unravel the underlying role of GINS2 in liver carcinogenesis and tumor progression, we compared DEGs in the TCGA dataset between GINS2high and GINS2low groups determined by the GINS2 median cutoff." (PMID 35069907, 2022). "Our study findings confirm that the expression of GINS2 in different types of tumours is associated with gene expression in immune checkpoints." (PMID 36466552, 2022). "Moreover, GINS2 was associated with tumor immunity and may be a potential immunotherapeutic target for OS." (PMID 36873736, 2023). "Moreover, the underlying functional and mechanistic basis of GINS2 in tumor proliferation and TME remain unknown." (PMID 35069907, 2022). "Various key regulators (CALR, MSI2-Numb, ZNF263/ZNF31, and GINS2) play significant roles in promoting EMT following genomic alterations under different tumor microenvironment conditions." (PMID 39781447, 2025). "GINS2 knockdown suppressed proliferation, colony formation, migration, and invasion in vitro, and inhibited tumor growth in vivo." (PMID 41322418, 2025). "Consistent with the in vitro results, GINS2 knockdown led to a significant suppression of xenograft tumor growth, resulting in substantially smaller tumor volumes and lower tumor weights compared to the control group after 4 weeks." (PMID 41322418, 2025). "Crucially, depleting these neutrophils using an anti-Ly6G antibody significantly attenuated the tumor-promoting effect of GINS2 overexpression, demonstrating that TANs are key mediators of GINS2’s oncogenic function." (PMID 41322418, 2025). "We demonstrate that GINS2 promotes tumor cell proliferation, migration, and invasion, potentially involving interaction with PTP4A1 and PKM2." (PMID 41322418, 2025). "Critically, the addition of anti-PD-L1 antibody to the T cell + neutrophil + sh-GINS2 group resulted in the most significant suppression of tumor volume and weight." (PMID 41322418, 2025). "GINS2 expression showed significant positive correlation with estimated tumor purity (Rho=0.278), and also exhibited a significant negative correlation with CD8+ T cell infiltration levels estimated by the MCP-counter algorithm (Rho=0.18)." (PMID 41322418, 2025). "To determine if these recruited neutrophils contribute to GINS2-driven tumor progression, we performed a neutrophil depletion study." (PMID 41322418, 2025). "Tumor sphere formation assays demonstrated that the partial stemness of GINS2 KO cells was restored when ECT2 was overexpressed." (PMID 38467631, 2024). "Bioinformatic analysis of samples from The Cancer Genome Atlas (TCGA) and Genotype-Tissue Expression portal corroborated that GINS2 mRNA was significantly upregulated in tumor tissues compared with normal tissues (P < 0.05)." (PMID 38467631, 2024). "Since GINS2 has been reported to be involved in multiple signaling pathways in a wide spectrum of cancer types, the core mechanism of GINS2-mediated tumor progression is still unclear." (PMID 36873736, 2023). "Mechanically, LC-MS, CoIP, and rescue experiments revealed that GINS2 promoted tumor progression through the STAT3/MYC axis in the OS." (PMID 36873736, 2023). "Previous studies reported that GINS2 promoted tumor growth by regulating specific downstream signaling pathways." (PMID 36873736, 2023). "Conversely, M2 traditionally regarded as promoting tumor growth by suppressing cell-mediated immunity and subsequent cancer cell killing, was significantly elevated in GINS2." (PMID 36345721, 2022). "The results showed that the expression of GINS2 is significantly correlated with methyltransferases and MMR proteins in various tumours, indicating the critical relationship between GINS2 and tumour immunity." (PMID 36466552, 2022).